PIK3CA (phosphatidylinositol-4,5-bisphosphate 3-kinase catalytic subunit alpha)
Diseases named in the same sentence as PIK3CA in open-access papers (continued):
Sharing a sentence is not in itself a finding about the gene and the disease.
tumor (continued). "The analysis of single nucleotide variants in KRAS, NRAS, PIK3CA, BRAF, and EGFR using cfDNA has been shown to have >80% concordance when compared to tumor tissue of colorectal, lung, and breast cancer patients." (PMID 30364656, 2018). "A mouse model engineered to conditionally express PIK3CA (H1047R) has revealed that focal amplification of either MET or c-MYC was present in tumours which reoccurred after PIK3CA inactivation." (PMID 29374181, 2018). "The results of this study showed that KRAS and NRAS mutataions are usually present in the large majority of tumor cells, whereas BRAF and PIK3CA mutations often affect a limited, subclonal fraction of tumor cells." (PMID 29652830, 2018). "The most frequently mutated genes across all tumor types included KRAS, PIK3CA, BRAF, EGFR, NRAS and ERBB2." (PMID 29854313, 2018). "Thirty-one cfDNA samples positive for IDH1, KRAS, PIK3CA, NRAS, AKT, BRAF, and IDH2 mutations in tumor tissue were selected for ddPCR, MassARRAY and NGS comparison." (PMID 29535804, 2018). "In our preclinical xenograft model, the combination of both esiRNAs is more effective than the single esiRNA application to inhibit tumor growth caused by simultaneous interference with KRAS and PIK3CA expression." (PMID 30001368, 2018). "We chose heterogeneous endoribonuclease-prepared siRNA pools (esiRNAs) against the frequently mutated genes PIK3CA and KRAS and coupled them to the anti-EGFR antibody cetuximab, which was internalized specifically into the tumor cells." (PMID 30001368, 2018). "PX-866 induced cessation of tumor growth in xenograft models of human HNSCC which included one case of PIK3CA gene amplification and another case of E545K." (PMID 31093356, 2018). "In four cases, tumours were wild type in primary sites, but were RAS mutant type in lung metastatic sites; in another 1 case, gene mutation changed from KRAS G12D and PIK3CA E545A in primary site to wild type in lung metastatic site." (PMID 30171333, 2018). "All but one patient with PIK3CA-mutated tumor died of CRC; the only one who was alive 168 months since the initial diagnosis had PIK3CA R88Q mutation." (PMID 30018674, 2018). "The most frequently mutated genes across all tumor types included KRAS (30 patients), PIK3CA (16 patients), BRAF (6 patients), EGFR (5 patients), NRAS (4 patients), and ERBB2 (3 patients)." (PMID 29854313, 2018). "Our study provides mechanistic and in vivo evidence indicating a role for MAP3K1 as a tumor suppressor gene at least in the context of PIK3CA-mutant backgrounds." (PMID 29765551, 2018). "The method successfully identified two PIK3CA H1047R positive patient samples from a test set of available tumour biopsy DNA samples purified either from fresh frozen tumour tissue or from formalin fixed paraffin embedded (FFPE) material." (PMID 29523855, 2018). "Meanwhile, the expression levels of LGR5 and c-myc were also increased in PIK3CA mutant tumor tissues comparing with wild type tumors Further immunobloting analysis was also performed with CC-1 cells." (PMID 29970892, 2018). "Presence of KRAS, PIK3CA, and BRAF mutations was tested in cfDNA and tumor tissue with an overall concordance rate of 76% for KRAS, 88% for PIK3CA, and 97% for BRAF mutations." (PMID 29441349, 2018). "On the other hand, PIK3CA mutation is associated with phosphorylated AKT expression to decrease apoptosis and increase tumor invasion." (PMID 29069792, 2017).
tumor (continued). "We propose that mutation of PIK3CA alters the activity of other genes involved in tumor aggressiveness, and that inhibiting PIK3CA modulates these altered pathways." (PMID 28427202, 2017). "We therefore assessed the relationship between clinicopathologic factors including RAS, PIK3CA, and BRAF tumor mutation status and PFS." (PMID 28068936, 2017). "NGS-based profiling of the tumor genome identified a single nonsynonymous mutation among the many genes noted for recurrent mutations in CRC (e.g., KRAS, NRAS, BRAF, PIK3CA) and a striking focal amplification of the FGFR2 gene." (PMID 28835367, 2017). "From the 22 samples analysed, five KRAS (codon 12 and 13), two BRAF(V600E) and 2 PIK3CA mutants were identified, including one tumour with a BRAF and PIK3CA mutation." (PMID 28931905, 2017). "It suppresses spheroid growth, invasion and epithelial-to-mesenchymal transition (EMT) in PIK3CA-mutated LSCC cells, and reduces tumor growth and mesenchymal phenotype in xenograft mice." (PMID 28592260, 2017). "Five patients (20.0%) with PIK3CA altered tumors also had PTEN mutations, while 1 patient (4.0%) had a dual PIK3CA and AKT1 mutated tumor." (PMID 28178681, 2017). "The alternative pathway is that the co‐initiating clone(s) acquire additional genetic or epigenetic damage and progress to become the predominant tumor clone(s), generating carcinomas with PIK3CA or KRAS mutant subpopulations." (PMID 28755461, 2017). "Plasma protein levels of VEGF and EGF, gene mutations of KRAS, BRAF and PIK3CA, and expression of P27, phosphorylated EGFR and AKT in tumor tissues were also investigated for their potential roles as biomarkers of clinical outcomes." (PMID 28288572, 2017). "Mutations in the PIK3CA oncogene were associated with higher estimates of CD8+ T cells and NK cells, along with decreased Treg/CD8 ratios, across multiple tumor types." (PMID 28749946, 2017). "GATK-based analysis of OV10 also detected a large insertion in PIK3CA, a missense variant in ARID1A (p.Ala532Thr) observed in only 2/25 tumor and 0/100 normal reads, and an NF1 large insertion that introduces a stopgain." (PMID 28852190, 2017). "The tumor samples of nine patients were confirmed to show PTEN loss by IHC and one GC with the PIK3CA mutation was found by target sequencing." (PMID 28330462, 2017). "In our molecular analysis, we detected and verified mutations in genes such as ARID1A, CTNNB1, PIK3CA, and PTEN which are frequently affected in these tumour entities." (PMID 28103826, 2017). "The agreement between PIK3CA mutation status in FFPE samples and circulating tumor DNA (ctDNA) was moderate (K = 0.591; 95% IC = 0.371–0.811)." (PMID 28330468, 2017). "PIK3CA, BRAF and KRAS somatic mutations are relatively common in type I tumours, with each subtype exhibiting distinct molecular profiles." (PMID 28117679, 2017). "We also noted associations of several cancer driver mutations in genes such as PIK3CA, BRAF, RAS family members, and FGFR3, with estimates of immune infiltrate, although these associations were often observed in limited tumor types." (PMID 28749946, 2017). "Of the POLE‐mutated CRCs, one tumor was microsatellite‐stable and the other had low microsatellite instability, whereas KRAS and PIK3CA mutations were found in one tumor each." (PMID 29072370, 2017). "The anti-proliferative and pro-apoptotic effects of BKM120 are proven in tumor cells, irrespective the PIK3CA status." (PMID 29113422, 2017). "In contrast, PIK3CA mutations are relatively rare in malignant melanoma (~3%), despite the critical role of PTEN inactivation in this tumor type." (PMID 28353628, 2017). "This tumor was also investigated for KRAS, NRAS, BRAF, and PIK3CA mutations, and a mutation in KRAS exon 4 was found, namely the c.351A>C, p.Lys117Asn." (PMID 29072370, 2017).
tumor (continued). "The ORRs of patients with a PIK3CA or BRAF tumor mutation were very low (28.6%), and more than 40% of patients with a BRAF tumor mutation had confirmed disease progression at the first evaluation." (PMID 28068936, 2017). "Overall, we found a moderate agreement between PIK3CA mutation status in plasma and FFPE tumor samples (K = 0.591; 95% IC = 0.371–0.811)." (PMID 28330468, 2017). "Our results are in contrast to NeoALTTO, where patients treated with a combination of weekly paclitaxel, trastuzumab and lapatinib who had PIK3CA-WT tumours had a pCR rate of 53.1%, which decreased to 28.6% in patients with tumours harbouring PIK3CA mutations." (PMID 28750640, 2017). "This is a very interesting result showing that PIK3CA is not only important for the tumor in the initial phase but that tumors still rely on its activity even a few months after induction." (PMID 28445948, 2017). "The PIK3CA and KRAS mutations analyzed in this study are recognized hotspot point mutations, meaning they are overrepresented in tumor sequence databases compared to most other mutations." (PMID 28755461, 2017). "The ability of PIK3CA of detecting neoplasms, its usefulness in monitoring tumor progression, as well as the influence of UV exposure on PIK3CA mutations have been subject to extensive research." (PMID 28127430, 2017). "Hypermorphic mutations in PIK3CA and PIK3R1 genes, coding for the p110α and p85α proteins, are prevalent in numerous tumor types as verified by deep sequencing analyses in the frame of projects such as TCGA." (PMID 28143957, 2017). "As such, there are insufficient data to justify the exclusion of patients with a RAS, PIK3CA, or BRAF tumor mutation from Bmab treatment regimens." (PMID 28068936, 2017). "This tumor was BRCA1 mutated, and had an observed increase in expression in AKT3 and PIK3CA, and a significant decrease in expression of PTEN, demonstrating an active PI3K/AKT pathway." (PMID 28649657, 2017). "Derived from a recurrent tumor in a PIK3CA-H1047R inducible transgenic mouse in which the tumor partially regressed and then recurred following transgene shutoff by Dox withdrawal." (PMID 28430642, 2017). "Meyer, Brinkhaus found that expression of the PIK3CA mutant with H1047R was sufficient to induce tumor formation in transgenic mice." (PMID 29228676, 2017). "Multivariate analysis that included RAS, PIK3CA, and BRAF tumor mutations and baseline prognostic variables revealed that liver metastasis, unresectable primary tumor, RAS and BRAF tumor mutations had independent prognostic value for early progression." (PMID 28068936, 2017). "While the exact function of PIK3CA in DIPG in clonal and subclonal tumor evolution remains undefined, spatial tumor conservation of PIK3CA further supports the therapeutic advantage of targeting the RTK–PI3K–MAPK pathway." (PMID 28401062, 2017). "Surprisingly, the recurrence rates of the PIK3CA-mutantation/SHC1-loop+ luminal A tumor patients were lower in the first 5 years after diagnosis than PIK3CA-mutantation/SHC1-loop− luminal A tumor patients (P < 0.01, log-rank test)." (PMID 28392480, 2017). "In a PIK3CA-dependent murine xenograft model, alpelisib showed significant dose-dependent inhibition of tumor growth and a favorable safety profile." (PMID 28108737, 2017).
tumor (continued). "PIK3CA and/or ERBB family mutations were detected in 23 (31.1%) tumour samples tested, whereas PTEN expression was low in 31.1% of cases tested." (PMID 28750640, 2017). "PIK3CA has been shown to be important for tumor cell survival, adhesion, motility and proliferation." (PMID 28404905, 2017). "We generated two transgenic mouse models expressing the human PIK3CA‐H1047R‐ and the ‐E545K hotspot‐mutant genes in the mammary gland and evaluated their effects on development and tumor formation." (PMID 28296140, 2017). "We investigated the mRNA expression of PIK3CA, and found it increased from primary tumor to paired metastases within paired samples (p = 0.031)." (PMID 28860563, 2017). "It selectively inhibits wild type and mutant forms of PI3Kα with equivalent potency and induces apoptosis and growth inhibition in mutant PIK3CA tumour models." (PMID 28806782, 2017). "It was also shown that a combination of buparlisib with the anti-EGFR monoclonal antibody cetuximab exerts a synergistic effect on tumor inhibition in wild-type or PIK3CA mutant HNSCC cell lines as well as in a xenograft model of HNSCC." (PMID 28108737, 2017). "In contrast, in the TCHL arm, patients with PIK3CA and/or ERBB family mutated tumours were more likely to achieve a pCR than patients with PIK3CA and ERBB WT tumours (77.8% vs. 35%; p = 0.05)." (PMID 28750640, 2017). "In this study, we found that patients with a RAS, PIK3CA, or BRAF tumor mutation had a lower ORR than patients with tumors that did not carry these mutations, although this difference was not statistically significant." (PMID 28068936, 2017). "Mutations in PIK3CA (25.9%), INPP5B (30.8%), SRC (99%) and TSC2 (46.7%) were observed in Tumor #3, and Tumor #4 harbored an NF1 gene mutation (43.5%)." (PMID 27057633, 2016). "The main intrinsic parameters of this pathway that have been assessed in tumor models as biomarkers of sensitivity, alone or in combination, are the loss of PTEN function, AKT phosphorylation, and PIK3CA mutations." (PMID 27374081, 2016). "The PIK3CA gene, which encodes the catalytic subunit pf PI3K, is mutated at a high frequency in gastric cancer cell lines and tumor tissues." (PMID 26701847, 2016). "We found that ESR1 mutations showed a trend towards higher prevalence in patients with tumours classified as luminal A by PAM50 compared with luminal B (41.4 versus 31.8%), as well as in patients with tumours harbouring PIK3CA mutations (44.4%)." (PMID 27174596, 2016). "On the other hand, although PIK3CA had a high ONC score in both ER+ (94%) and ER− (81%) tumours, the domains in which the recurrent mutations occurred differed." (PMID 27161491, 2016). "Stable knockdown of mutant E545K/E545G PIK3CA in three UC cell lines reduced PIK3CA protein levels by up to 92 % and was associated with reduced AKT activation, proliferation and in vivo tumor growth." (PMID 27465249, 2016). "However, subtype of PIK3CA mutation may impact the tumor recurrence and survival, because few E545K mutants in our cohort, the relationship involved in this analysis may be not robust, then further studies or pool analysis of reported researches may focus on this." (PMID 27074743, 2016). "Specifically, PIK3CA and KIT mutations were detected in 16 (47.0%), and 8 (23.5%), respectively, of the tumor specimens." (PMID 26968814, 2016).
tumor (continued). "According to previously accepted models of tumor progression and metastatic dissemination punctuated by colonial expansions, the incongruity of PIK3CA genotype between primary and metastatic lesions could also compromise the diagnostic performance of PIK3CA mutation detection in cfDNA." (PMID 27336598, 2016). "When mutant KRAS co-exists with mutant PIK3CA in the same tumor, the protein levels of autophagic factor LC3 are recorded high." (PMID 26802026, 2016). "For example, tumor A00021 had both AKT1 E17K (27.9%) and BRAF G469A (19.7%) mutations, and tumor A00026 had both BRAF D594G (26.7%) and PIK3CA E542K (15.6%) mutations." (PMID 26989027, 2016). "PIK3CA amplification was defined as PIK3CA/centromere 3 ratio is ≥ 2.0 or average number of PIK3CA signals/tumor cell nucleus ≥ 5.0." (PMID 27095573, 2016). "Together, these data suggest that upregulation of GPT2 by PIK3CA mutations produces more α-KG from glutamine to replenish the TCA, thereby generating more ATP and intermediates for macromolecule synthesis to sustain rapid growth of PIK3CA mutant tumours." (PMID 27321283, 2016). "“With regard to PIK3CA, hotspot mutations...” were frequently detected in CTC of operable BC and MBC patients which changed during tumor progression resulting in a worse outcome." (PMID 27223437, 2016). "Tumor #1, in addition to the mutations observed in Tumor #2, also harbored mutations in CBL (56.7%), PIKFIVE (21%), PIK3CA (38.2%), and PIK3R3 (25%)." (PMID 27057633, 2016). "Mutations in KRAS, NRAS, BRAF, and PIK3CA genes were evaluated for association with several pathological parameters: sex, age at diagnosis, anatomical location of primary CRC, tumour grading, AJCC stage of the disease." (PMID 27737711, 2016). "Specifically, KRAS, PIK3CA and KIT mutations were detected in 31/48 (64.6%), 11/48 (22.9%), 8/48 (16.7%) tumor specimens, respectively." (PMID 26968814, 2016). "Consistently, AOA treatment reduces amounts of α-KG and alanine, but increases amount of pyruvate and glutamate, in PIK3CA mutant xenograft tumours." (PMID 27321283, 2016). "In a second MCF7 model (Y537S ER, E545K PIK3CA), we observed increased tumor growth inhibition when fulvestrant was combined with palbociclib or everolimus." (PMID 27472462, 2016). "The stem cell marker ALDH1 was found to be the most prominent expressed gene with an expression rate of 85.7%, whereas AKT2 and PIK3CA were found in 50.0% and 42.9% of the tumour cells, respectively." (PMID 27302574, 2016). "Genomic DNA was isolated from formalin-fixed, paraffin-embedded primary tumour tissue samples of CRC patients and screened for mutations in RAS and BRAF genes, using pyrosequencing assays, and in PIK3CA gene, using automated DNA sequencing assays." (PMID 27737711, 2016). "We found that loss of the tumor suppressors PTEN and INPP4B occurred with high frequencies in TNBC PDX, while PIK3CA and AKT1 mutations were rare." (PMID 27374081, 2016). "The PTEN and PIK3CA alterations occur early in breast tumor initiation and seem to be present in dominant tumor clones." (PMID 27374081, 2016). "HR+ patients with a PIK3CA mutant tumor had a favorable disease-free survival (DFS; HR 0.66, P=0.05), however, the prognostic effect was specific to luminal A patients (Luminal A: HR 0.67, P=0.1; Luminal B: HR 1.01, P=0.98)." (PMID 28721382, 2016).